DPP4 (dipeptidyl peptidase 4)
Diseases named in the same sentence as DPP4 in open-access papers (continued):
Sharing a sentence is not in itself a finding about the gene and the disease.
diabetes (continued). "Little is known about body composition changes in type 2 diabetes mellitus (T2DM) patients on insulin therapy who use sodium–glucose cotransporter-2 (SGLT2) inhibitors versus dipeptidyl peptidase-4 (DPP4) inhibitors." (PMID 36224294, 2022). "It has been shown that DPP4 activity correlated with the onset and severity of obesity and diabetes, and plasma DPP4 activity was elevated in type 2 diabetes mellitus and obesity." (PMID 35883204, 2022). "On the other hand, the discovery that leech extract has ACE and DPP4 inhibitory activity provides new evidence for treating hypertension and diabetes with the traditional Chinese medicine leech." (PMID 36080189, 2022). "Glucagon-like peptide-1 receptor agonists and dipeptidyl peptidase-4 inhibitors are commonly used treatments for patients with type 2 diabetes mellitus (T2DM)." (PMID 35986429, 2022). "DPP-4 inhibitors improve glucose metabolism and are clinically used for the treatment of diabetes mellitus." (PMID 35123462, 2022). "Serum levels and activity of DPP4 are altered in many pathophysiological conditions, namely in obesity and diabetes." (PMID 35190847, 2022). "Circulating soluble DPP-4 levels are high in patients with diabetes mellitus, and DPP4, which is bound to urinary microvesicles, can be useful for staging diabetic kidney disease." (PMID 35897725, 2022). "Antioxidants derived from plants with antidiabetic qualities, such as acting as DPP-4 inhibitors, are regarded to be the most effective strategy for keeping a normal β-cell physiology and treating diabetes." (PMID 36440220, 2022). "The strong association between GLP-1R gene polymorphisms and the hypoglycemic effects of DPP-4 inhibitors and GLP-1RAs makes the GLP-1R gene a candidate gene for precision medicine in diabetes." (PMID 36528605, 2022). "Incretin mimetics, also known as glucagon-like peptide-1 (GLP-1) agonists, and dipeptidyl peptidase-4 (DPP4) inhibitors are both common classes of drugs used in the treatment of diabetes." (PMID 36225477, 2022). "Retrospective observational studies previously reported improvement among patients with Type 2 diabetes mellitus using drugs specifically designed to inhibit DPP4 activity and COVID-19 in severe outcomes and mortality." (PMID 35195023, 2022). "The most common oral diabetes treatment at baseline was metformin (40.33% of patients), followed by sulfonylureas (24.16%) and DPP-4 inhibitors (22.25%)." (PMID 35456224, 2022). "Sitagliptin is an effective inhibitor of dipeptidyl peptidase 4 (DPP-4) for the treatment of diabetes, which is recently reported to regulate oxidative stress and autophagy." (PMID 35635037, 2022). "Diabetes-related retention of stem/progenitor cells in the bone marrow involves altering the dipeptidyl peptidase-4/stromal-derived factor-1 alpha (DPP-4/SDF1-α) axis, which is essential to establish a cytokine gradient towards the peripheral blood." (PMID 35204091, 2022). "The DPP-4 levels in the SAT were positively correlated with atherosclerosis, diabetes mellitus, DPP-4-inhibitor use, and fasting blood glucose." (PMID 35893426, 2022). "Fortunately, most diabetes therapies, including metformin, thiazolidinediones, and dipeptidyl peptidase-4 inhibitors, have been shown to have a neutral or favorable effect on arrhythmia risk." (PMID 35892445, 2022). "Before admission, 72% of the treated diabetes group received a dipeptidyl peptidase-4 inhibitor, 40% metformin, 8% pioglitazone, 44% sodium glucose transporter 2 inhibitors, 4% glucagon-like peptide 1 analog, and 12% insulin." (PMID 35079646, 2022). "Considering the higher reporting frequency of ketoacidosis observed with dapagliflozin then DPP-4 inhibitors or insulins, attention should be given to patients treated with this drug." (PMID 35337085, 2022). "This strategy was also used to modify the dipeptidyl peptidase-4 gene (DPP-4) to upregulate the glucagon-like peptide 1 in a murine model of type 2 diabetes mellitus (T2DM) db/db mice." (PMID 36092658, 2022).
diabetes (continued). "Surprisingly, some patients in our study received other diabetes drugs (namely metformin, DPP4 inhibitors, SGLT2 inhibitors, and GLP1 receptor analogs) besides their insulin regimen." (PMID 35101023, 2022). "CD26/dipeptidyl peptidase 4 (DPP4) is a clinically proven molecular target of diabetes-controlling drugs but the DPP4 gene control of dysglycaemia is not proven." (PMID 35190847, 2022). "In order to further elucidate the molecular mechanisms underlying the memory enhancing effect of novel adamantane derivatives and DPP4 inhibitors, we have examined the gene expression levels of Bdnf and Cav1 in the hippocampal tissues of diabetes mice." (PMID 35468904, 2022). "The length of diabetes in only DPP4 inhibitor treated group was 3 subjects for more than 10 years, 1 subject for 8 years, 3 subjects for 5 years, 1 subject for 4 years and 3 subjects for 2 years." (PMID 35351190, 2022). "Actually, CD26 inhibitor, also known as DPP4 inhibitor or gliptin, are a class of oral hypoglycemic drugs that antagonize the enzyme DPP4 and are approved to treat diabetes mellitus type 2 (DM-II)." (PMID 35163100, 2022). "DPP-4 is a major target for diabetes, as its inhibitors potentiate the effects of the incretin hormones." (PMID 36547924, 2022). "To reveal the possible mechanism of how DPP-4 inhibitor saxagliptin alleviates cognitive dysfunction in the diabetics, we investigated the neuron apoptosis in the hippocampus area of these rats." (PMID 39280108, 2022). "DPP4 inhibitors and IL-6 antagonists can be considered to reduce the effect of COVID-19 infection on patients with diabetes." (PMID 34996987, 2022). "DPP-4 inhibitors are a class of oral hypoglycemics that block the enzyme DPP-4 for treating diabetes." (PMID 35496279, 2022). "Omarigliptin is an inhibitor of dipeptidyl peptidase-4 (DPP-4) developed for the treatment of diabetes." (PMID 35389830, 2022). "At present, dipeptidyl peptidase-4 (DPP-4) inhibitors are widely used in initial monotherapy or combination therapy for treating diabetes." (PMID 36547924, 2022). "In this work, we demonstrate the potential protective effects of adipose-derived cell treatment in modulating diabetes-induced DPP4 activity, insulin resistance, and systemic inflammation." (PMID 35883204, 2022). "Specifically, DPP4 inhibitors have been shown to mitigate endoplasmic reticulum stress, which often occurs in the beta cells of patients with diabetes, while also aiding in insulin production to compensate for this stress." (PMID 35229479, 2022). "Omarigliptin is a long-acting dipeptidyl peptidase 4 (DPP-4) inhibitor for the treatment of diabetes." (PMID 35389830, 2022). "Due to its ability to prevent the inactivation of GLP-1, DPP4 inhibition (DPP4i) was explored as a target for the treatment and management of type 2 diabetes mellitus (T2DM) in the 1990s." (PMID 35630534, 2022). "Six months before his admission, rash emerged on his trunk and upper limbs after the administration of linagliptin, a dipeptidyl peptidase-4 (DPP-4) inhibitor, for his diabetes." (PMID 35799119, 2022). "We also found that several molecules implicated in obesity, diabetes, and hypertension, appear to show interactions with SARS-CoV-2 proteins as well as human proteins (ACE2 and DPP4)." (PMID 35611169, 2022). "Dipeptidyl peptidase 4 inhibitor (DPP4i) is an effective medicine for type 2 diabetes mellitus (T2DM)." (PMID 35672759, 2022). "Our study demonstrated that new adamantane derivatives, similarly to DPP4 inhibitors, can restrict diabetes-induced cognitive deficits." (PMID 35468904, 2022). "One possibility is that DPP4 inhibitor and metformin combination group consisted with patients with longer duration of diabetes period (23 subjects were diabetes for more than 10 years)." (PMID 35351190, 2022). "Background and Introduction: Saxagliptin is a hypoglycemic drug that acts as a dipeptidyl peptidase-4 (DPP-4) inhibitor and is preferably used in the treatment of Type 2 Diabetes Mellitus (T2DM)." (PMID 36364338, 2022).
diabetes (continued). "CD26/DPP-4 is targeted by inhibitors for the treatment of type-2 diabetes mellitus, Crohn’s disease and other inflammatory or autoimmune conditions and has been implicated in a wide variety of cancers." (PMID 35371018, 2022). "Further, the data provide explanation for the mechanism of the reno-protective effect of SGLT2i and possibly DPP4 inhibitors as well in diabetes." (PMID 36313818, 2022). "A variety of DPP-4 inhibitors have been widely used in the treatment of diabetes, among which the effect of saxagliptin on blood glucose control is higher than other oral hypoglycemic drugs." (PMID 39280108, 2022). "Fewer patients with diabetes in Asia were treated with insulin and/or biguanides, and roughly twice as many patients in Asia were treated with dipeptidyl peptidase-4 inhibitors compared with patients in Europe or Latin America." (PMID 35497805, 2022). "We aimed to investigate the acute effects of breakfast fruits meal sequence and postprandial exercise on the blood glucose level and dipeptidyl peptidase 4 (DPP4) activity among type 2 diabetes mellitus patients." (PMID 36204396, 2022). "Current studies have shown that DPP4 inhibitors can be considered as the preferred hypoglycemic regimen in the treatment of patients with diabetes with COVID-19 infection." (PMID 34996987, 2022). "Sitagliptin is a dipeptidyl peptidase-4 (DPP-4) inhibitor that is used orally in conjunction with diet and exercise to control sugar levels in type 2 Diabetes Mellitus patients." (PMID 35294449, 2022). "Dipeptidyl peptidase-4 inhibitors (DPP-4i) decrease glucose levels by regulating incretin peptides in type 2 diabetes mellitus (T2DM)." (PMID 35164839, 2022). "In the clinical perspectives of DPP4 inhibitors in the prevention and treatment of HCC, a nationwide study in Taiwan demonstrated that DPP4 inhibitors decreased the risk of HCC in patients with chronic hepatitis C and type 2 diabetes mellitus." (PMID 35053615, 2022). "The length of diabetes in DPP4 inhibitor and metformin combination treated group was 23 subjects for more than 10 years, 5 subjects for 5 years, 3 subjects for 2 years and 3 subjects for a year." (PMID 35351190, 2022). "Collectively, these results indicate that diabetes induces DPP4 expression and suppress insulin-induced Akt activation in the liver, and the injection of non-diabetic plasma into the adipose tissue of diabetic animals reverses those effects." (PMID 34043673, 2021). "Linagliptin is a dipeptidyl peptidase-4 inhibitor that reduces blood sugar by increasing insulin and decreasing glucagon production by the pancreas, used to treat diabetes mellitus type 2." (PMID 33525510, 2021). "The levels of plasma DPP4 activity are elevated in diseases, including type 2 diabetes mellitus (T2DM), obesity, and atherosclerosis." (PMID 34043673, 2021). "DPP-4 inhibitors are a class of diabetes medications that are used with diet and exercise to control high blood sugar in adults with type 2 diabetes." (PMID 33850463, 2021). "Widely used oral drugs to control hyperglycemia in patient with diabetes are metformin, dipeptidyl peptidase 4 (DPP4) inhibitors, and SGLT2 inhibitors." (PMID 33581737, 2021). "In conclusion, the present study showed that in STZ-induced diabetes model, increased liver DPP4 activity significantly enhanced the tissue oxidative stress and activated NFκB signaling pathway, and further induced chronic liver inflammation." (PMID 34493714, 2021). "Compared with treatment episodes with sulfonylureas, a larger proportion of the treatment episodes with DPP4 inhibitors were from patients with diabetes complications and with concurrent use of other glucose-lowering medications." (PMID 34254177, 2021). "Later, DPP-4 immunoreactive cells localized in the rat taste buds with significantly higher expression of DPP-4 mRNA in the rats with diabetes." (PMID 33477478, 2021).
diabetes (continued). "Naringin is abundant in orange peel and has been shown to inhibit DPP-4 in vitro and in vivo and to enhance insulin levels, and thus, is considered an option for the low-cost treatment of diabetes." (PMID 34203048, 2021). "Sitagliptin (STG) is a representative DPP-4 inhibitor and is widely used in treating type 2 diabetes mellitus (T2DM)." (PMID 34789244, 2021). "Dipeptidyl peptidase-4 (DPP-4) inhibitors exert hypoglycemic effects by inhibiting the degradation of glucagon-like peptide-1 (GLP-1) in patients with type 2 diabetes mellitus." (PMID 34067150, 2021). "As CD26 plays an important role in blood glucose level regulation by cleaving Glucagon-like-peptide 1 (GLP-1), CD26/DPP-4 inhibitors are widely used in the treatment of diabetes mellitus." (PMID 33889154, 2021). "Dipeptidyl peptidase-4 (DPP-4) inhibitors are well-known effective potential agents against type 2 diabetes mellitus (DM)." (PMID 33567615, 2021). "DPP4 is an aminopeptidase that plays a critical role in glucose metabolism, and DPP4 inhibitors have been approved for the treatment of type 2 diabetes mellitus." (PMID 33562193, 2021). "Participants took the following medications for diabetes: Metformin (62.5%), Repaglinide (31.25%), DPP-4 inhibitor (31.25%), Sulfonylurea (18.75%), GLP -1 (6.25%), SGLT2i (6.25%), insulin (6.25%)." (PMID 34404385, 2021). "DPP4 inhibitors, an emerging drug for diabetes treatment, have been found to exhibit renoprotective effects in addition to glucose-lowering effects." (PMID 34950037, 2021). "Because the major targets of DPP-4 are incretin hormones that regulate insulin secretion, DPP-4-inhibitors have been broadly used to treat type 2 diabetes mellitus." (PMID 33401457, 2021). "DPP-4 inhibition has become a staple of diabetes management, with a plethora of drugs now available since the approval of sitagliptin (Januvia®) in 2006." (PMID 34081167, 2021). "Dipeptidyl peptidase-4 (DPP-4) inhibitors were used by 22% of patients receiving a treatment for diabetes in 2016." (PMID 34256874, 2021). "Increased M1 expression induces DPP4 activity in plasma and upregulates inflammatory mediators in liver that subsequently lead to systemic inflammation and insulin resistance in diabetes." (PMID 34043673, 2021). "The aim of our retrospective study was to investigate the potential of Dipeptidyl-peptidase 4 (DPP4)-inhibitors, which are safe Food and Drug Association (FDA)-approved drugs for treating diabetes, in treating CRC patients." (PMID 34298800, 2021). "Lobeliae Chinensis Herba (LCH), a traditional Chinese herb widely used in the treatment of diabetes, has recently been found to have a hypoglycaemic mechanism related to the inhibition of DPP4." (PMID 34950037, 2021). "The aim of this study was to investigate whether the use of DPP-4 inhibitors is associated with a decreased risk of hepatocellular carcinoma (HCC) in patients with diabetes mellitus (DM) and chronic HCV infection." (PMID 34604157, 2021). "Glucagon-like peptide 1 receptor agonists and dipeptidyl-peptidase 4 inhibitors are medications used for managing diabetes, mimicking the metabolic effects of incretin hormones." (PMID 34007411, 2021). "Altogether, our results demonstrate that diabetes induces adipose tissue and liver DPP4 expression as well as plasma DPP4 activity." (PMID 34043673, 2021). "Non-diabetic plasma reverses M1/M2 cytokine expression, plasma CCL2 levels, DPP4 activity, and Kupffer cell activation in diabetes." (PMID 34043673, 2021). "Second, patients with type 2 diabetes mellitus in East Asia are characterized by more remarkable β‐cell dysfunction and less insulin resistance than in Caucasians, and DPP4 inhibitors seem to exert better glycemic control in East Asians." (PMID 33995274, 2021). "Commercially available CD26/DPP4 inhibitors are thus widely employed as an accompanying therapy in the treatment of diabetes mellitus type 2." (PMID 34885056, 2021).
diabetes (continued). "Sitagliptin (STG), a classical DPP4 inhibitor, has been widely used for type 2 diabetes mellitus treatment." (PMID 34926239, 2021). "In Japan, DPP4 inhibitors have become the first-line antidiabetic drugs and more than 70% of the diabetes patients are being treated with incretin-based therapies." (PMID 33995274, 2021). "Firstly, DPP-4 inhibitors were used a lot in treatment programs of clinical trials such as a DPP-4 inhibitor versus placebo/metformin/other anti-diabetes drugs or a DPP-4 inhibitor/anti-diabetes drugs versus other anti-diabetes drugs." (PMID 34384428, 2021). "The treatment with a DPP-4 inhibitor significantly improved wound healing, angiogenesis and endogenous progenitor cell recruitment in the setting of diabetes." (PMID 34212057, 2021). "Our findings conclude that CRC patients with diabetes and treated with DPP4-inhibitors in our hospital during 2006–2015, their 5-year prognosis following curative resection was significantly better than those treated with metformin." (PMID 34298800, 2021). "The increased activities of DPP-4 and PTP-1B are associated with the occurrence of insulin resistance and diabetes." (PMID 34659435, 2021). "Spinal application of DPP4-inhibitors, which are widely used clinically in the treatment of diabetes mellitus, decreases mechanical allodynia in inflammatory pain and shows a modest antihyperalgesic effect following partial SNL in male rats." (PMID 34331199, 2021). "Trelagliptin is a long-acting inhibitor of DPP-4 used for the management of type 2 diabetes mellitus." (PMID 33734011, 2021). "Our results suggest M1/M2 cytokine expression in adipose tissue is critical in diabetes-induced DPP4 activity, liver inflammation, and insulin resistance." (PMID 34043673, 2021). "In addition, treatment with the DPP4 inhibitor sitagliptin after surgery for colorectal or lung cancer in patients with diabetes was associated with greater overall survival than treatment with other diabetic medications, suggesting that sCD26/DPP4 may have a role in regulating anti-tumor activity." (PMID 33757558, 2021). "The elucidation of the incretin-insulin pathway prompted the development of DPP-4 inhibitors to prolong the circulating half-life of endogenous incretins to achieve glycemic control in diabetes patients, with a focus on drugs that can be taken orally." (PMID 34205264, 2021). "Proline-specific DPPs are emerging drug targets, and DPP4 inhibitors (gliptins) are already approved globally for the treatment of diabetes." (PMID 33810334, 2021). "In summary, we demonstrate the involvement of M1/M2 cytokine expression in diabetes-induced DPP4 activity, insulin resistance, and systemic inflammation." (PMID 34043673, 2021). "As an example, plasma DPP4 activity in Diabetes mellitus type 2 patients was attributed to the enhanced release of sCD26/DPP4 from circulating TH17 cells." (PMID 35003134, 2021). "Teneligliptin, which belongs to the family of dipeptidyl peptidase-4 inhibitors, is used to treat type 2 diabetes mellitus (T2DM)." (PMID 34512362, 2021). "This study investigated the therapeutic effect of already approved drugs, DPP4-inhibitors, which are commonly prescribed to treat diabetes." (PMID 34298800, 2021). "LCH is belonging to the family Campanulaceae and has recently been identified as a potential target of DPP4 for the treatment of diabetes through network pharmacology." (PMID 34950037, 2021). "The elevated expression of the DPP4 enzyme has been found in the elderly and also in many patients with diabetes or other metabolic disorders." (PMID 35822018, 2021). "Their predictions prompted the authors to suggest linagliptin, a DPP‐4 inhibitor and approved anti‐diabetes drug, as a repurposed drug candidate against the ongoing COVID‐19 pandemic." (PMID 33348462, 2021). "DPP-4 inhibition likely alters the degradation and regulation of peptides in the lumen and thus influences tubular structure and function in diabetes." (PMID 34697593, 2021).